FBH1 (F-box DNA helicase 1)
Description:
3'-5' DNA helicase and substrate-recognition component of the SCF(FBH1) E3 ubiquitin ligase complex that plays a key role in response to stalled/damaged replication forks. Involved in genome maintenance by acting as an anti-recombinogenic helicase and preventing extensive strand exchange during homologous recombination: promotes RAD51 filament dissolution from stalled forks, thereby inhibiting homologous recombination and preventing excessive recombination. Also promotes cell death and DNA double-strand breakage in response to replication stress: together with MUS81, promotes the endonucleolytic DNA cleavage following prolonged replication stress via its helicase activity, possibly to eliminate cells with excessive replication stress. Plays a major role in remodeling of stalled DNA forks by catalyzing fork regression, in which the fork reverses and the two nascent DNA strands anneal. In addition to the helicase activity, also acts as the substrate-recognition component of the SCF(FBH1) E3 ubiquitin ligase complex, a complex that mediates ubiquitination of RAD51, leading to regulate RAD51 subcellular location.
Synonyms: hFBH1; FBX18; FBXO18; FLJ14590
Tractability: PROTAC: UniProt records ubiquitination sites on it; ubiquitination databases record sites on it.
Gene: Protein-coding gene on chromosome 10 (5,890,203 to 5,937,594, forward strand). Ensembl gene ENSG00000134452.
Subcellular location: Nucleus; Chromosome
Gene Ontology:
Molecular function: 3'-5' DNA helicase activity; ATP hydrolysis activity; DNA helicase activity; DNA translocase activity; double-stranded DNA binding; protein binding; single-stranded DNA binding; ATP binding; DNA binding; hydrolase activity
Biological process: DNA catabolic process; DNA damage response; DNA repair; negative regulation of double-strand break repair via homologous recombination; positive regulation of intrinsic apoptotic signaling pathway in response to DNA damage; positive regulation of protein phosphorylation; protein ubiquitination; replication fork processing; response to intra-S DNA damage checkpoint signaling; double-strand break repair via homologous recombination; SCF-dependent proteasomal ubiquitin-dependent protein catabolic process
Cellular component: chromatin; chromosome; nucleus; SCF ubiquitin ligase complex
Genetic constraint (gnomAD): Loss-of-function variants: 39 observed, 113.53 expected, observed/expected ratio (o/e) 0.34, 90% interval 0.26 to 0.45. The upper end of that interval is the gene's LOEUF score, 0.45, which puts it in group 1 of 6, group 1 being the genes least tolerant of losing a copy. Missense variants: 997 observed, 1,382.8 expected, observed/expected ratio (o/e) 0.72, 90% interval 0.68 to 0.76. Synonymous variants: 523 observed, 527.02 expected, observed/expected ratio (o/e) 0.99, 90% interval 0.92 to 1.07.
Homologues: Orthologues: chimpanzee FBH1 (99% identical), macaque FBH1 (98% identical), dog FBH1 (92% identical), rabbit FBH1 (91% identical), mouse Fbh1 (90% identical), rat Fbh1 (90% identical), guinea pig FBH1 (86% identical), pig FBH1 (81% identical), tropical clawed frog fbh1 (52% identical), zebrafish fbxo18 (45% identical).
Diseases named in the same sentence as FBH1 in open-access papers:
FBH1 is named in the same sentence as 9 diseases in open-access papers, as found by Europe PMC text mining. Sharing a sentence is not in itself a finding about the gene and the disease. The quoted sentences say what the papers report.
breast carcinoma (4 papers, 2012 to 2023). "We find that mutations in FBH1 co-occur with mutations in the breast cancer susceptibility gene BRCA2 and other DNA damage repair genes." (PMID 37760409, 2023).
melanoma (1 paper, 2025). A malignant, usually aggressive tumor composed of atypical, neoplastic melanocytes. "FBH1 is deleted or mutated in a high frequency of melanoma cell lines and protects melanocytes from UV-mediated transformation." (PMID 40672194, 2025). "FBH1 loss has been linked to melanoma and mutation or loss of FBH1 may be present in additional tumors." (PMID 40672194, 2025).
cancer (3 papers, 2014 to 2025). A tumor composed of atypical neoplastic, often pleomorphic cells that invade other tissues. "We discuss how loss and gain of FBH1 in a wide variety of cancers can contribute to tumor-associated phenotypes, impact cancer therapies and be exploited for potential targeted therapies." (PMID 40582249, 2025). "Our data show that FBH1 mutations occur in nearly every cancer, while certain cancers are affected by changes in gene expression or copy-number variation, either amplification or reduction in copy number." (PMID 37760409, 2023). "Nevertheless, FBH1 mutations are expected to contribute to the overall mutation burden in cancer cells." (PMID 37760409, 2023). "As expected, FBH1 mutations have been detected in cancer cells, but a comprehensive analysis of these mutations has not yet been carried out." (PMID 37760409, 2023). "Here, we analyzed reported FBH1 mutations in cancer cells using the Catalogue of Somatic Mutations in Cancers (COSMIC) to understand how they interact with the BRCA2-BRCA1-PALB2." (PMID 37760409, 2023). "In this report, we used artificial intelligence algorithms to characterize mutations, gene expression changes, and copy-number variations appearing in cancer cells with the goal to map the FBH1 mutation spectrum." (PMID 37760409, 2023). "Further analysis of Fbh1 function in human cancer cells should increase our understanding of the role this protein plays during tumorigenesis." (PMID 25165823, 2014). "Here we queried all FBH1 genetic alterations in human cancers using the data de-posited on COSMIC." (PMID 37760409, 2023). "Interestingly, a recent classification of driver genes in cancer cells did not include FBH1 suggesting that changes in its activity (either loss- or gain-of-function) does not significantly impact cellular transformation and immortalization." (PMID 37760409, 2023). "Thus, although we do not have the information for FBH1, it is possible that heterozygous mutations contribute to cancer development for two reasons: they may act as dominant, or they cause haploinsufficiency." (PMID 37760409, 2023).
FBH1 also shares sentences with these, for which no sentence is quoted: tumor (2 papers); cervical carcinoma (1); Crohn disease (1); endometrial cancer (1); infection (1); Parkinson disease (1).